MYC (MYC proto-oncogene, bHLH transcription factor)
Diseases named in the same sentence as MYC in open-access papers (continued):
Sharing a sentence is not in itself a finding about the gene and the disease.
tumor (continued). "In CRC, circCCDC66 sponged miRNA-33b and miR-93 to protect the MYC mRNA so that tumor proliferation, migration, and metastasis were activated in both in vitro and in vivo." (PMID 31737058, 2019). "There are currently ongoing studies with anti MYC compounds in animal models in conjunction with chemotherapy for other tumor types." (PMID 31842352, 2019). "Our working model indicates a coordinated interplay between the components of the DNA methylating and demethylating machinery contributing to MYC-driven tumor maintenance, highlighting the potential of specific TET enzymes for therapeutic strategies." (PMID 31266538, 2019). "Originated from the same company, the benzoisoxazoloazepine CPI0610 was assessed in in vivo studies in mice, where its tumor reducing activity appeared to correlate with a BET-driven reduction in MYC gene expression." (PMID 31581671, 2019). "Expression analyses revealed a clear up-regulation of c-MYC and E2F transcription factor in tumor samples compared to their corresponding normal tissues showing also a correlation with splicing factors." (PMID 31316092, 2019). "We have also validated the significance of these findings using clinical samples by demonstrating that CDK1high tumor samples displayed upregulation of MYC target genes, which were reported to overlap with SOX2 targets." (PMID 31080551, 2019). "Consistently, depleting XBP1s either by the IRE1α RNase-specific inhibitor MKC8866 or siRNA-mediated knockdown results in reduced c-MYC levels and tumor regression." (PMID 30679434, 2019). "Apoptosis and senescence represent two tumor-suppressive mechanisms which can be modulated by MYC and RAS oncogenes." (PMID 31341534, 2019). "Downstream genes activated by STAT3 have been associated with tumor proliferation and survival, including PIM1/PIM2, MYC, BIRC5 and BCL2L134–39." (PMID 30741931, 2019). "Glutaminolysis in tumor cells can be MYC-dependent and feeds mitochondrial metabolism through TCA cycle anaplerosis." (PMID 31416205, 2019). "Genetic alterations that result in changes to MYC, such as MYC amplification, can dysregulate its normal function and alter the balance between being a tumor suppressor versus being tumorigenic." (PMID 30704460, 2019). "It reveals a coordinated interplay between the components of the DNA (de)methylating machinery that contribute to MYC-driven tumor maintenance, highlighting the potential of specific TET enzymes for therapeutic strategies." (PMID 31266538, 2019). "Accordingly, by using double sequential immunostaining, a significant fraction of STAT3+ tumor cells in a set of basal-type MIBC co-expressed MYC and FOSL1." (PMID 31438567, 2019). "The most prominently studied case is SRSF1, which is upregulated in different human tumor types, and regulates the splicing of many genes encoding cancer-related proteins such as BIN1, which normally inhibits cMYC (MYC)." (PMID 31162605, 2019). "In conclusion, we propose that the combination of cell death-inducing AB therapy together with anti-PD-1 immunotherapy provides a potent tumor-targeting strategy with high translational potential in tumor types with high MYC expression." (PMID 30728358, 2019). "Since sorafenib is the first-line drug approved by FDA, we compared the anti-tumor effect of JQ1 with sorafenib, showing that JQ1 had more promising anti-tumor effects than sorafenib in HCC cells expressing relatively high level of MYC in vitro and in vivo." (PMID 30770740, 2019).
tumor (continued). "Transcriptome analysis of a Hippo-deficient gastric cancer model showed that TEAD activation directly upregulates MYC and its target genes, which, in turn, induced tumor progression." (PMID 31212916, 2019). "MYC mRNA levels were higher in 39 of the 41 tumor samples than the normal mucosa of the same patients, while APC mRNA levels were lower in the majority of cancer samples." (PMID 31623618, 2019). "We and others have demonstrated that cellular senescence accompanied by extensive chromatin remodeling is an important mechanism of tumor regression upon MYC inactivation in T-ALL, and other cancer types." (PMID 31266538, 2019). "Activation of ATR-mediated signalling is a key compensatory response to mitigate replication stress in MYC overexpressed tumours." (PMID 30746633, 2019). "For 7 SCC-distinguishing enzymes (ASNS, GAPDH, GOT2, IDH2, ME1, PSAT, and TPI) protein levels were increased in MYC+N1ICD tumours compared with the normal lungs." (PMID 31114017, 2019). "Inhibition of endogenous MYC led to a significant decrease in infiltrating macrophage and neutrophil frequencies and resulted in tumor regression." (PMID 31831007, 2019). "The impairment of tumor cell metabolism arises due to MYC deactivation as a result of the SRC-p38 MAPK-4EBP1 signaling." (PMID 31641103, 2019). "As noted in the introduction, our previous attempts to delay tumor onset in LMP2A/λ-MYC and λ-MYC mice by blocking S10 phosphorylation alone were unsuccessful." (PMID 30992353, 2019). "Under mechanical context, YAP1 coordinates with E-cadherin, β-Catenin, and MYC and integrates multiple signaling pathways to contribute to tumor growth." (PMID 30934860, 2019). "Our integrate approach revealed a profound effect of MYC overexpression on tumor evolution and identified MCL1 as a critical and druggable dependency in BRCA1-deficient TNBC with high expression of MYC." (PMID 30674894, 2019). "Here, gene expression analyses in patients diagnosed as NMIBC were performed to determine those molecular pathways involved in tumor initiation, finding that both MYC and E2F are up regulated and helps to tumor initiation and progression." (PMID 31316092, 2019). "This protein modulates cell polarization, adhesion, and migration in tumor-derived cells and is strongly associated with cancer metastasis and the expression of oncogenic factors that include KRAS, MYC, and MDR1." (PMID 31796082, 2019). "SPAG5 promotes tumor growth and DNA repair by increasing c-MYC transcriptional activity via interaction with MYCBP." (PMID 30736840, 2019). "Her-2+ and PAM50.Her-2 subtypes were more common in tumours with low MYC mRNA and low ATM mRNA expressions (all adjusted p values ≤ 0.01)." (PMID 30746633, 2019). "In the present study, we focused on the potential utility of droplet digital polymerase chain reaction (ddPCR) in detecting c-MYC GCN gain in tumor tissue and cell-free plasma of CRC patients, as a prognostic marker." (PMID 30733532, 2019). "MYC plays a central role in the recruitment of angiogenic proteins, especially in rapidly proliferating tumor tissues, with high levels of hypoxia." (PMID 31645899, 2019). "Transient MYC knockdown for 31 days greatly slowed tumor growth and abrogated the survival benefit of olaparib, consistent with in vitro results." (PMID 31266951, 2019). "We concluded that transcriptional repression at high MYC levels involves a decrease in transcription elongation that contributes to the establishment of tumor-specific gene expression signatures." (PMID 30928206, 2019). "Addition of CPI203 to lenalidomide therapy further decreased tumor burden in mice, which was accompanied by simultaneous MYC and IRF4 downregulation and induction of apoptosis." (PMID 30906568, 2019).
tumor (continued). "Accordingly, IQS-01.01RS and CPI203 combinatorial treatment achieved a synergistic downregulation of MYC an improved tumor growth inhibition in DLBCL cell lines and xenograft model." (PMID 31581671, 2019). "Tumour cells overexpressing MYC meet their high energy demands by increased glucose uptake, glycolysis, lactate production and amino acid consumption." (PMID 31028445, 2019). "Here, we reveal a novel mechanism through which MYC establishes and maintains tumor cell-specific DNA (hydroxy)methylation and gene expression programs in a genome-wide fashion." (PMID 31266538, 2019). "Thus, chronically elevated MYC levels may not be able to sustain pro-apoptotic levels of AMPK-BIM activity long-term and it is tempting to speculate that pharmacological stimulation of AMPK reactivates the MYC-associated apoptotic machinery intrinsic to tumor cells." (PMID 30728358, 2019). "This suggests that tumor cells need to acquire additional alterations in other, collaborating cancer driver genes to counteract MYC-induced apoptosis." (PMID 30674894, 2019). "Cho-miR159 loading by A15-Exo significantly reduced TCF7 and MYC expression in tumors, with decreased tumor cell proliferation and increased apoptosis, which were still observed in the Co-A15-Exo group." (PMID 31481080, 2019). "As a result, we demonstrated that the anti-tumor effects of JQ1 were more potent than those of sorafenib in MYC-positive HCC cell lines." (PMID 30770740, 2019). "Recently, an important study revealed that FTO expression is upregulated in IDH-mutant leukemia and plays an anti-tumor role through the FTO/m6A/MYC/CEBPA signaling pathway." (PMID 30810537, 2019). "MYC, which is over-expressed in a variety of tumors, plays important roles in tumor proliferation, apoptosis and tumorigenesis." (PMID 30791942, 2019). "The oncogenic role of CCAT2 has been recognized in large part by virtue of an epigenetic mechanism involving its proximity with MYC and acting as a sponge through its interaction with some tumor suppressor miRNAs, such as miR-145 and miR-216b." (PMID 31398859, 2019). "The identification and further characterization of these clients of the HSP70/BAG1 complex provides the initial step towards targeted therapies that can convert MYC from a pro-tumorigenic oncogene to a pro-apoptotic tumor suppressor." (PMID 30902071, 2019). "IDH2 was upregulated in both human SCCs and AdCs, whereas all three isoforms were upregulated in MYC+N1ICD tumours." (PMID 31114017, 2019). "As a whole, our gene expression data indicate that an up-regulation of E2F family and MYC participates in both initiation and tumor progression through recurrence, regulated by epigenetic mechanisms." (PMID 31316092, 2019). "In our previous studies, the Cks1 knockout alone increased p27Kip1 levels in LMP2A/λ-MYC mice nearly to wild-type levels but resulted in only a partial delay in tumor development." (PMID 30992353, 2019). "Our results reveal that the MYC oncogene establishes and maintains tumor cell-specific DNA (hydroxy)methylation patterns on a genome-wide level by modulating the expression of individual components of the DNA methylating and demethylating machinery." (PMID 31266538, 2019). "The combination of MYC, BCL2, and P53dd led to tumor formation with a median of 111 days and the combination of MYC, BCL2, and BCL6 resulted in tumor formation with a median of 108 days." (PMID 31586074, 2019). "We also previously demonstrated that a Cks1 knockout partially delayed tumor onset in LMP2A/λ-MYC mice, but onset was still significantly faster than that in λ-MYC mice." (PMID 30992353, 2019). "The antitumorigenic effect of AAV-mediated miR-26 replacement strategy was previously reported in a c-MYC transgenic model of liver cancer, resulting in inhibition of cancer cell proliferation and tumor progression." (PMID 31805631, 2019).
tumor (continued). "Our results show that tumor onset in LMP2A/λ-MYC/p27Super mice was significantly later than that in λ-MYC mice and was not significantly different from that in λ-MYC/p27Super mice." (PMID 30992353, 2019). "In these analyses, we found that MYC alterations were significantly more common in liver lesions (12% compared with 3–6%) than in primary tumours (FDR-adjusted q-value = 0.004)." (PMID 31292535, 2019). "Like SCCs, MYC+N1ICD tumours had elevated levels of 13C incorporation into the 4-13C position of the glutamate residue of GSH+GSSG, despite having similar levels of the labelled glutamate precursor, which was consistent with the increased RNA levels of GSS." (PMID 31114017, 2019). "The AKT/ERK/c-MYC signaling pathway played an important role in the ZCCHC13-evoked increase in tumor cell growth." (PMID 30940166, 2019). "We believe that the GSEA of the MYC signature comprehensively evaluated changes in many genes affected by MYC, thus better reflecting the activity of MYC in the tumor than the MYC mRNA level or copy number." (PMID 31848373, 2019). "Although JQ1 is still being evaluated in phase I and II clinical trials for the treatment of advanced malignancies, emerging evidence demonstrated that the anti-tumor effect of JQ1 was limited in tumor cells with high level of MYC protein." (PMID 30770740, 2019). "While the exact role of TET1 and TET2 in regulating DNA (hydroxy)methylation outside of developmental processes is not well understood, our findings indicate distinct functions of TET1 and TET2 in MYC-driven tumor maintenance." (PMID 31266538, 2019). "MYC mediates global metabolic reprogramming to match the enhanced demand for anabolic metabolites in tumor cells." (PMID 31856871, 2019). "In summary, we demonstrated that JQ1 has more potent anti-tumor effects than sorafenib in MYC-overexpressing HCC cells." (PMID 30770740, 2019). "Doxycycline-induced cells express approximately 3∗106 MYC molecules per cell and display tumor-specific gene expression patterns." (PMID 30928206, 2019). "Our study sought to determine EBV IgG in serum, EBER-1 and MYC in tumours sections in children and adolescent diagnosed with BL at Moi Teaching and Referral Hospital (MTRH) in Eldoret, Kenya." (PMID 32180880, 2019). "For example, pathway enrichment for cell proliferation and tumor stem cells, including genes such as MYC, NFκB, and WNT, was more relevant in TNBC than in nTNBC subtypes." (PMID 31572452, 2019). "During this process, broad changes occur in histone methylation (increase of H3K9me3) and acetylation (decrease of H4ac), suggesting that during tumor maintenance MYC maintains large areas of active chromatin." (PMID 31266538, 2019). "Bridging integrator 1 (BIN1) has showed outstanding tumor-suppressive potential via inhibiting c-MYC-mediated tumorigenesis." (PMID 31496920, 2019). "We found that JQ1, a commonly used BET bromo-domain inhibitor, offered a better anti-tumor response than sorafenib in MYC-positive HCC cells by inducing apoptosis in vitro and in vivo." (PMID 30770740, 2019). "In short, HACER is able to identify diverse tumor-specific MYC enhancers/super-enhancers, differing in size and location, and consistent with previous studies." (PMID 30247654, 2019). "Targets of the let-7 family include the oncogenes RAS and MYC, making let-7 family members veritable tumor-suppressing miRNAs." (PMID 31627266, 2019). "It has been accepted that deregulated MYC critically leads to cell transformation and tumor progression." (PMID 30934860, 2019). "We demonstrate here that it is specifically the S isoform of BAG1 that provides the survival function in MYC overexpressing tumor cells." (PMID 30902071, 2019). "Previous studies showed that both D281G and R248W mutants transactivate expression of tumor progression-related genes such as MYC, PCNA, EGFR, and EGR1; the D281G mutant shows an even greater transactivating activity than R248W in these studies." (PMID 30862120, 2019).
tumor (continued). "Tumor samples were also collected 5 days after drug treatment for immunohistochemical analysis of MYC expression, tumor cell proliferation, and apoptosis (Ki67 and cleaved caspase 3)." (PMID 31752970, 2019). "In keeping with this finding, c-MYC immunohistochemical staining intensity was significantly weaker in xenograft tumor sections from MKC8866-treated mice compared with untreated mice." (PMID 30679434, 2019). "Consistently, the reduced tumor weight under HOXC-AS1 suppression was restored by overexpression of MYC in vivo." (PMID 31870402, 2019). "In cancer, the polycomb protein BMI1, in cooperation with MYC, promotes tumor development by repressing tumor-suppressor genes, such as INK4A and ARF." (PMID 33912356, 2019). "MYC paralog activation is important for tumorigenesis and tumor maintenance, which would make MYC an ideal target for therapeutic intervention." (PMID 31375684, 2019). "We next evaluated how gene expression of selected metabolic genes translates into protein expression in MYC+N1ICD tumours." (PMID 31114017, 2019). "The tumors derived from HOXC-AS1-silenced AGS cells were smaller in size and grew slower than those from shCtrl-transfected control cells, and overexpression of MYC recovered the tumor size and tumor growth." (PMID 31870402, 2019). "Conversely, it is unlikely that a further increase in global transcription rate accounts for the selective pressure to increase MYC levels during tumor progression." (PMID 30928206, 2019). "Therapy-naïve CRC cells with high c-MYC expression progress more quickly, and CRC metastases exhibit greater c-MYC expression than the primary tumor." (PMID 31491003, 2019). "Several orthotopic murine models of MYC-driven group 3 oncogenesis have attempted to clarify MYC involvement in MB tumor initiation, maintenance, and progression and provide models for new therapeutic strategies." (PMID 30876441, 2019). "In our previous study, median tumor-free survival in LMP2A/λ-MYC/Cks1−/− mice was delayed only 61.5 days compared to that in LMP2A/λ-MYC mice." (PMID 30992353, 2019). "As miR‐34a‐5p has tumor suppressor activity by both targeting MYC and stimulating apoptosis, while repressing cell cycle progression and metastasis, it is an attractive target for novel anticancer therapies." (PMID 30451365, 2019). "We demonstrate that pharmacological reactivation of MYC-dependent apoptosis is a powerful antitumor strategy involving both tumor cell depletion and immunosurveillance." (PMID 30728358, 2019). "Here, we showed that the high expression of CDK5 neutralized the tumor suppressing effect of BIN1 by phosphorylating c-MYC at Ser-62 site." (PMID 31496920, 2019). "We evaluated the expression of 22 of the genes in the SCC-distinguishing metabolic gene signature in MYC+N1ICD tumours by qPCR." (PMID 31114017, 2019). "We evaluate MYC dependency in vivo and characterise the histological and mRNA expression changes that occur in these MYC-driven tumours." (PMID 31350286, 2019). "Among the most commonly altered of the regulatory genes that are involved in cellular metabolism were PIK3CA (in 32% of tumours), MYC (in 14%) and HIF1A (in 11%)." (PMID 31754644, 2019). "Noteworthy, inhibitors of BET proteins directly downregulate MYC expression and suppress tumor growth in vivo." (PMID 30967773, 2019). "Previously, shRNA-mediated inhibition of SAE2, or its binding partner SAE1, in HMECs overexpressing a MYC-oestrogen receptor fusion transgene was shown to induce spindle defects, polyploidy, apoptosis and tumour regression." (PMID 31455158, 2019). "Interaction between an enhancer region downstream the first transcriptional start site of PVT1 and the PVT1 promoter itself has tumor suppressor activity by reducing MYC transcription." (PMID 30451365, 2019). "De novo purine synthesis is highly elevated in GBM stem cells and promotes cell growth and tumor formation, which is mediated and maintained by the activity of c-MYC." (PMID 31450721, 2019).